KLF4 (KLF transcription factor 4)
Diseases named in the same sentence as KLF4 in open-access papers (continued):
Sharing a sentence is not in itself a finding about the gene and the disease.
colorectal cancer (continued). "This review will focus on the roles KLF4 and KLF5 play in colorectal cancer." (PMID 37173904, 2023). "Exosomes from colorectal cancer cells contained miR-25-3p, which regulate vascular permeability and angiogenesis by suppressing the expression of Kruppel-like factor 2 (KLF2) and Kruppel-like factor 4 (KLF4)." (PMID 34239869, 2021). "For example, miR-25-3p is known to play an important role in facilitating colorectal cancer metastasis and promoting angiogenesis by targeting KLF (Kruppel-like factor)-2 and KLF-4, which implies that miR-25-3p can be a promising target for treating colorectal cancer." (PMID 33028046, 2020). "In addition, Krüppel-like factor 4 (KLF4), a tumor suppressor in HCC, has been reported to be up-regulated by the PPARγ agonist troglitazone and promotes cell cycle arrest in colorectal cancer cells." (PMID 27483249, 2016). "Although it has been reported recently that miR-103 was expressed in colorectal cancer as an oncogenic miRNA by targeting DAPK, KLF4 and PER3, the detail mechanism of miR-103 in colorectal cancer growth and metastasis is still largely unknown." (PMID 24828205, 2014). "Furthermore, overexpression of klf4 in the human RKO colon cancer cell lines resulted in reduced tumorigenecity, suggesting klf4 is a tumor suppressor gene in colorectal cancer." (PMID 21687630, 2011). "Exosomal miR-25-3p derived from Colorectal cancer (CRC) cells could be absorbed by endothelial cells to facilitate, angiogenesis and increasing vascular permeability via targeting KLF2 (kruppel like factor 2) and KLF4 (kruppel like factor 4)." (PMID 35255950, 2022). "Moreover, Klf4 has been described to inhibit cell growth and play a tumor suppressive rather than an oncogenic role in colorectal cancer." (PMID 24204315, 2013).
colon carcinoma (86 papers, 2005 to 2026). "Survival analysis showed that the differential expression of SPP1, CFRT, and KLF4 were associated with poor prognosis in colon cancer." (PMID 35733095, 2022). "After investigating RNA-miRNA pairs and validating as before, colon tumors exhibited loss of miR-145 with increased Serpine1 and gain of mir-34a with reduced Klf4." (PMID 34494932, 2021). "The prior investigation of high-abundance miRNAs in rat colon tumors highlighted a role for c-Myc, Oct-3/4, and Sox2, whereas the present work has implicated a fourth ‘defined factor’ for pluripotency, namely KLF4." (PMID 23006636, 2012). "There was an inverse association between miR-206 levels and KLF4 mRNA expression among the 21 human primary colon cancers examined (inset, r2 = 0.525, P < 0.05)." (PMID 23006636, 2012). "Conversely, KLF4 deficiency accelerated the progression of colitis and colon cancer." (PMID 37031197, 2023). "Aberrant KLF4 is associated with overexpression of IFITM3 in colon cancer." (PMID 33364194, 2020). "Moreover, in a large cohort of colon cancer, loss of KLF4 expression is an indicator for poor prognosis including survival." (PMID 23919723, 2013). "Over-expression of KLF4 in colon cancer cells caused inhibition of DNA synthesis and cell growth." (PMID 23024650, 2012). "For example, Krüppel-like factor 4 (KLF4) is a transcription factor implicated in colon cancer." (PMID 16321147, 2005). "However, loss of KLF4 was associated with worse disease-free survival in colon cancer patients." (PMID 27314328, 2016). "Intriguingly, a reverse scenario unfolds in colon cancer tissues, where KLF4 levels are diminished while pVHL expression surges." (PMID 40034124, 2025). "This notion is further substantiated by the observation that replenishing pVHL triggers cell cycle arrest due to the cumulative buildup of KLF4 and the subsequent upregulation of p21 within colon cancer cells." (PMID 40034124, 2025). "NPR3 was shown to be down-regulated upon KLF4 overexpression in a transfected colon cancer cell line." (PMID 38830769, 2024). "LUM was shown to be down-regulated upon KLF4 overexpression in a transfected colon cancer cell line." (PMID 38830769, 2024). "For example, constitutive expression of KLF4 in fibroblasts or colon cancer cells resulted in the inhibition of DNA synthesis." (PMID 37723138, 2023). "For example, in colon cancer KLF4 is a potent tumor suppressor, while in melanoma KLF4 expression promotes cell proliferation." (PMID 37614497, 2023). "Sulforaphane, a natural compound derived from broccoli, inhibited the progression of colon cancer by inducing KLF4 and enhancing the KLF4-p21 signaling." (PMID 37031197, 2023). "Reports have indicated that the overexpression of KLF4 in several cell lines, including a human colon cancer cell line, induces cell cycle arrest by blocking G1/S progression." (PMID 35637963, 2022). "Previous studies unraveled that transcription factor KLF4 level in colon cancer and pancreatic cancer is considerably reduced, but its upstream regulatory factor is still unclear." (PMID 35027543, 2022). "Supporting this possibility is our data with KLF4 agonist APTO-253 that suppresses colon tumor organoid growth by promoting differentiation." (PMID 36276637, 2022). "It was reported that colon cancer cells with decreased KLF4 expression are refractory to chemotherapy." (PMID 33986248, 2021). "Reduced KLF4 is documented in rat41,42 and human colon tumors, suggesting an avenue for precision nutrition in the clinical setting." (PMID 34494932, 2021). "On the other hand, KLF4 is required for maintaining cancer stem cell populations in breast and colon cancer cells, and KLF4α, an alternative spliced KLF4 isoform, was identified to act as an oncogene in pancreatic cancer." (PMID 32350244, 2020). "KLF4 can also indirectly modulate the actin cytoskeleton morphology via activity of RhoA in order to inhibit cellular migration and invasion of the human colon cancer cell line RKO." (PMID 33266506, 2020).
colon carcinoma (continued). "It has also been shown that cotransfection of KLF4 with HDAC3 synergistically represses cycling B1 transcription in human colon cancer cells." (PMID 30936247, 2019). "Indirect downregulation of matrix metalloproteinase 2 (MMP2) and E-cadherin by miR-29a-3p through Krüppel-like transcription factors 4 (KLF4) was reported in colon cancer cells." (PMID 29599914, 2018). "For instance, the silencing of the cofactor PATZ1 of KLF4 inhibits the colon cancer cell proliferation." (PMID 28684851, 2017). "Particularly, hsa-mir-7-2 is verified to negatively regulate the target KLF4 and promotes the progress of colon cancer since KLF4 is a tumor suppressor gene." (PMID 29513198, 2017). "contrast KLF4 expression was suppressed in KRASmut in colon cancer cells, which is consistent with its induction of multiple cell lineage differentiation in the intestine." (PMID 26744320, 2016). "Numerous studies have indicated that KLF4 overexpression predicts a better prognosis in several malignancies, including prostate cancer, colon cancer, urothelial cancer and gastric cancer." (PMID 27153563, 2016). "KLF4 was reported downregulated in esophageal cancer, gastric cancer, colon cancer, kidney cancer, liver cancer and bladder cancer, but overexpressed in breast cancer." (PMID 27531889, 2016). "KLF4, which has oncogenic properties in other cancers such as breast, skin and lung, functions as a tumor suppressor in colon cancer." (PMID 26186594, 2015). "Previous studies have shown that reprogramming of colon cancer cells using Oct3/4, Sox2, Klf4, and cMyc reduces cancer malignancy." (PMID 25970424, 2015). "Such an inhibitory role of miRNA in KLF4 expression of colon cancer was also found in miR-29a, of which miR-29 was upregulated in colon cancer tissues relate to normal mucosa." (PMID 26064956, 2015). "Tumor suppressive functions of KLF4 have been established in several human cancers, including colon cancer, gastric cancer, and bladder cancer." (PMID 25889839, 2015). "We retrovirally introduced a set of defined factors (OCT3/4, SOX2 and KLF4) into human colon cancer cells, followed by culture with conventional serum-containing medium, not human embryonic stem cell medium." (PMID 25006808, 2014). "In summary, we generated the cells with CSC properties: iCSCs, by introducing OCT3/4, SOX2 and KLF4 in the SW480 colon cancer cell line, and were able to isolate an iCSCs-enriched cell population by using Hoechst33342 staining and VM treatment." (PMID 25006808, 2014). "In the current study, we transduced OCT3/4, SOX2 and KLF4 into human colon cancer cells under the parental cell culture conditions and analyzed the transduced cells in terms of their CSC properties in vitro and in vivo." (PMID 25006808, 2014). "Upregulation of KLF4 has formerly been observed in early stages of colon carcinoma compared to normal mucosal levels." (PMID 24204315, 2013). "KLF4 expression is also a prognostic indicator for several tumor types, including head and neck squamous cell carcinoma, colon cancer, prostate cancer, and hepatic cancer." (PMID 23861801, 2013). "Using these CSC-enriched spheroid cells, we conclude that KLF4, which was previously thought to be a tumor suppressor, functions as an oncogene for the development of colon cancer." (PMID 23418515, 2013). "Taken together, culturing DLD-1 cells in serum-free medium enriches CSCs and the expression of KLF4 is essential for the characteristics of CSCs in DLD-1; thus KLF4 can be a potential therapeutic target for treating colon cancer." (PMID 23418515, 2013). "We first tried to confirm that the expressions of KLF4 in various colon cancer cell lines were lower than the normal colon epithelial cell lines as previously reported." (PMID 23418515, 2013).
colon carcinoma (continued). "Many groups reported that the KLF4 is expressed and functions as a tumor suppressor in colon cancer." (PMID 23418515, 2013). "Reconstitution of KLF4 in the colon cancer cell line RKO reduces colony formation, cell migration, and invasion." (PMID 23418515, 2013). "Our findings here also suggest that although KLF4 was reported as a tumor suppressor, it functions in colon CSCs-enriched spheroid cells for metastatic progression of colon cancer." (PMID 23418515, 2013). "Using a three-dimensional (3D) intestinal epithelial cyst formation assay, we found that KLF4 is essential for cell polarity and crypt-cyst formation in human colon cancer cells." (PMID 22384261, 2012). "Zhi and Tseng demonstrated that 15d-PGJ2 inhibits proliferation of HT-29 human colon cancer cells and induces upregulation of KLF4 mRNA and protein through the activation of MEK/ERK and STAT-dependent pathway." (PMID 23024650, 2012). "In this investigation of rat colon tumors, human primary colon cancers, and human colon cancer cell lines, the data supported an inverse trend between KLF4 and miR-206." (PMID 23006636, 2012). "An inverse correlation was noted between miR-206 and KLF4 in a panel of human primary colon cancers, which was supported by experimental studies involving knockdown and ectopic upregulation of miR-206 levels in human colon cancer cells." (PMID 23006636, 2012). "Upon further analysis, low KLF4 mRNA levels were detected in most colon cancers, with the exception of Cases 3 and Case 6 (normalized to GAPDH)." (PMID 23006636, 2012). "These colon tumors had the predicted inverse relationship with Klf4 mRNA levels, normalized to Gapdh." (PMID 23006636, 2012). "This investigation has focused on the possible role of miR-206 and one of its predicted targets, KLF4, in colon cancer development." (PMID 23006636, 2012). "Since KLF4 expression is dependent on CDX2 in human colon cancer cells, our finding is consistent with these reports and suggests that KLF4 regulates cell polarity through multiple genes, including LKB1." (PMID 22384261, 2012). "This investigation, therefore, sought to clarify the role of miR-206 and its putative target KLF4 in colon cancer development." (PMID 23006636, 2012). "KLF4 plays as a tumor suppressor in gastric cancer, colon cancer, esophagus cancer, bladder cancer, lung cancer and pancreatic ductal carcinoma." (PMID 21982273, 2011). "In RKO cells (human colon cancer-derived cells), KLF4 stimulates intestinal alkaline phosphatase (IAP) gene expression, through a critical region including the IF-III cis element located within the proximal IAP promoter region." (PMID 20119532, 2009). "In HCT-116 cells (human colon cancer-derived cells), KLF4 increases urokinase-type plasminogen activator receptor (uPAR)." (PMID 20119532, 2009). "However, reduction of TCF7L2 decreased transcriptional levels of Klf4 in Wnt overactivated colon tumors of mice." (PMID 40906297, 2025). "Next, we depleted CDX1 and KLF4 in SW1222 colon cancer cells by siRNA." (PMID 39472498, 2025). "Tumor spheroid models derived from sporadic colon cancer cell lines have been utilized to identify stem cell specific molecular markers including octamer binding transcription factor-4 (Oct-4), Kruppel-like factor-4 (Klf-4), sex determining region Y-box-2 (SOX-2) and cellular Myc (c-Myc)." (PMID 35269660, 2022). "In addition, important roles of Sp1 binding sites in Klf4 transcriptional activities have been demonstrated in colon cancer cells and smooth muscle cells." (PMID 33036290, 2020). "Interestingly, it has been reported that KLF4 levels are regulated by histone deacetylase inhibitors (HDACi) in colon cancer cell lines so we tested if in melanoma cells, HDACi treatment was able to induce KLF4 expression." (PMID 28412746, 2017). "Decreased KLF4 expression highly related to a poor survival in gastric cancer and colon cancer." (PMID 27531889, 2016). "In colon cancer stem cell-enriched spheroid cells, KLF4 acts as an oncogene." (PMID 27314328, 2016).
colon carcinoma (continued). "An inverse correlation was noted between miR-206 and KLF4 in a panel of human colon cancers." (PMID 26186594, 2015). "The transcription factor SOX2 is involved together with c-MYC, KLF4 and OCT3/4 in the induction and maintenance of pluripotent stem cells and has been also associated the expression of both SOX2 and β-CATENIN with metastases and poor prognosis in colon cancer." (PMID 24946763, 2014). "Thus, from our study, KLF4 most likely expresses in colon CSCs and acts as an oncogene for the development of colon cancer." (PMID 23418515, 2013). "However, the role of KLF4 in differentiated intestinal cells and colon cancer cells, as well as the mechanism by which it regulates homeostasis and represses tumorigenesis in the intestine is not well understood." (PMID 22384261, 2012). "KLF4 was induced by doxycycline in LS174T-KLF4 colon cancer cells." (PMID 22384261, 2012). "In order to confirm the role of KLF4 in facilitating cell polarity formation, 3D culture assay was performed in another colon cancer cell line to test whether KLF4 can enhance cyst formation in vitro." (PMID 22384261, 2012). "In a panel of primary human colon cancers, target validation at the mRNA and protein level confirmed a significant inverse relationship between miR-206 and KLF4, which was further supported by miR-206 knockdown and ectopic upregulation in human colon cancer cells." (PMID 23006636, 2012). "In colon cancers, KLF4 could be down-regulated by caudal type homeobox 2 (CDX2), notch signaling, transcription factor 4 (TCF4) or sex determining region Y-box 9 (Sox9)." (PMID 22937066, 2012). "In addition, KLF4 expression is stimulated following treatment of HT-29 colon cancer cells with IFN-γ and Stat-1 recruitment." (PMID 20119532, 2009). "Thus, whether KLF4 is expressed in colon CSCs and its functions of KLF4 in colon cancer need to be addressed." (PMID 23418515, 2013). "Furthermore, the recently new findings reveal more controversial role of KLF4 in tumorigenesis in one single tissue, such as the newly reported potential oncogenic role of KLF4 or KLF4 isoforms in pancreatic cancer, colon cancer and prostate cancer development." (PMID 23861801, 2013). "Thus, KLF4 has been thought to be a suppressor in the development of colon cancer." (PMID 23418515, 2013). "However, KLF4 also acts as a tumor suppressor in human colon cancer development." (PMID 23006636, 2012). "qPCR analysis also showed the downregulation of KLF4 and CTNNB1 upon synergistic activity of ZEB and VPA treated colon cancer cells." (PMID 42224286, 2026). "In addition, a previous study showed that in colon cancer, pVHL may be an oncogenic protein because it promotes proteasomal degradation of transcription factor Krüppel-like factor 4 (KLF4), which is involved in regulation of cell-fate decision as a tumor suppressor." (PMID 40906297, 2025). "Compared to control, expression levels of Klf4 significantly increased in AOM-DSS-induced colon tumors from cKO mice, while MEX3A overexpression in NCM460 cells downregulated KLF4 protein and restricted its nuclear localization." (PMID 36276637, 2022). "In contrast, some ZFPs from the KLF family are aberrantly expressed in colon cancer and have proliferation inhibitory effects, such as KLF5, KLF4, KLF6, and KLF3." (PMID 36358661, 2022). "For instance, in colon cancer, KLF4 inversely modulates IFITM3, and the dysregulation of KLF4 expression results in IFITM3 abnormal expression, which is the cause of progression and metastasis of cancer cells." (PMID 35027543, 2022). "We treated 3D cultures of Caco-2 colon cancer cells with BMP4 protein and it significantly upregulated KLF4." (PMID 36276637, 2022). "Colon cancer exosome miR-25-3p targets KLF2 and KLF4 of vascular endothelial cell, affecting their function." (PMID 34179017, 2021). "MYC, LEF1, KLF4, SALL4, and IRF4 were the five important TFs involved in the regulation of the immune response in colon cancer." (PMID 34938284, 2021).